MYCN (MYCN proto-oncogene, bHLH transcription factor)
Diseases named in the same sentence as MYCN in open-access papers (continued):
Sharing a sentence is not in itself a finding about the gene and the disease.
neuroblastoma (continued). "In both neuroblastoma cell lines, SP141 significantly inhibited MYCN expression at the 1.0 μM concentration." (PMID 33291373, 2020). "MYC and MYCN activate miR-9 inducing EMT in breast cancer and its expression is correlated with MYCN gene amplification in neuroblastoma." (PMID 32318352, 2020). "MYCN belongs to the MYC transcription factor family and is amplified in approximate 25% of neuroblastoma patients." (PMID 32593299, 2020). "We recently reported that MYCN controls the balance between SCD and ACD in human neuroblastoma cells." (PMID 33194665, 2020). "The oncogenes, including v-myc avian myelocytomatosis viral oncogene neuroblastoma derived homolog (MYCN) and Hypoxia-inducible factor (HIF)-1∝, were shown to regulate metabolism and mediate CDDP-resistance in neuroblastoma." (PMID 32927667, 2020). "In MYCamp-G3-MB, SPT16 does not fulfill the first two criteria despite exhibiting crucial cancer-dependency, whereas in another MYC family member driven malignant pediatric solid tumor, MYCN-amplified neuroblastoma (MYCNamp-NB), SPT16 is the major oncogenic player instead of SSRP142." (PMID 33268769, 2020). "MYCN and SLC19A1 mRNA expressions were decreased with pralatrexate in MYCN-amplified neuroblastoma cells." (PMID 32850011, 2020). "In neuroblastoma, TRIM32 interacts with MYCN and promotes its proteasomal degradation, which induces asymmetric cell division." (PMID 33173411, 2020). "Prior to selecting cell lines for MYCN and MYC profiling, we assessed RNA expression and protein expression across a subset of neuroblastoma cell lines." (PMID 32286315, 2020). "Thus, regulation of childhood height and pubertal timing through the Lin28/let‐7 axis may influence risk of MYCN‐dependent neuroblastoma in general, not necessarily only those tumors with genomic amplification of MYCN." (PMID 32945147, 2020). "Except MYCN amplification, MYCN protein expression, MYCN target gene CD44 and MYCN signature are used to predict the outcome of neuroblastoma." (PMID 32593299, 2020). "Here, we show that amplification of the MYCN oncogene and inactivation of the ATRX tumor-suppressor gene are mutually exclusive in neuroblastomas from patients of all ages and stages of disease." (PMID 32060267, 2020). "In two neuroblastoma and two retinoblastoma lines, the mechanism involved upregulation of MYCN RNA expression and translation, mediated by MDM2 interaction with the RNA in the neuroblastoma context." (PMID 33425720, 2020). "For example, MYCN and KRAS are prominently involved in neuroblastoma and colorectal cancer, respectively." (PMID 31992345, 2020). "MYCN amplification is the most important genomic feature in neuroblastoma (NB)." (PMID 33172452, 2020). "Altogether, these data from 4 different BRD4 PROTAC inhibitors indicate that PROTAC BRD4 inhibitors suppress MYCN or c-Myc expression by BET proteins depletion, thus inhibiting cell proliferation and inducing apoptosis in neuroblastoma cells." (PMID 33324552, 2020). "Specifically, the region with MYCN amplification had a high mitosis–karyorrhexis index and was less likely to have ultrabright telomere foci, characteristic of ALT, in ATRX-mutant neuroblastoma cells." (PMID 32060267, 2020). "Neuroblastoma (NB) with MYCN amplification has a poor prognosis and high mortality." (PMID 32569234, 2020). "We examined the effect of retinoic acid, the differentiation agent used in neuroblastoma therapy, on miR-506-3p, PLAGL2 and MYCN expressions by quantitative PCR and Western blots." (PMID 32087738, 2020). "Dual knockdown of the MYCN-targeted gene pair, MTHFD2 and PAICS, in MNA neuroblastoma cells synergically reduced cell proliferation, colony formation, migration ability, and DNA synthesis." (PMID 31624245, 2019). "In fact, we observed that MYCN frequently co-occupies the enhancers of target genes with LMO1, including those of CRC members, which characterize the ADRN subtype neuroblastoma." (PMID 31819055, 2019).
neuroblastoma (continued). "Here, we report that 4-hydroxychalcone is a potent cytotoxin for MYCN-amplified IMR-32 and SK-N-BE neuroblastoma cells, when compared to non-MYCN-amplified SH-SY5Y neuroblastoma cells and to the non-neuroblastoma human embryonic kidney cell line, HEK293t." (PMID 31885773, 2019). "In the whole genome neuroblastoma set, VCF2CNA identified MYCN high-level amplifications in 31 of 32 clinically validated samples compared to 15 found by CGI’s HMM-based CNA model." (PMID 31316100, 2019). "In line with the mRNA expression level after MYCN depletion, the protein level of ELOVL2 was also upregulated in both neuroblastoma cell lines." (PMID 31856871, 2019). "This mirrors what is already known in neuroblastoma cell lines and primary tumors in which the expression of MYC and MYCN are mutually exclusive." (PMID 31748534, 2019). "Of note, PIM inhibition sensitized both MYCN-amplified and wild-type, ALK-driven neuroblastoma cells to ALK inhibitors both in vitro and in vivo, suggesting co-inhibition of PIM and ALK as a viable strategy to enhance the efficacy of ALK inhibitors." (PMID 31780656, 2019). "Here, we discovered that MYCN inhibition lead to significant DHA accumulation and upregulated its synthesis enzyme ELOVL2 in neuroblastoma cell lines." (PMID 31856871, 2019). "We have previously demonstrated that N-Myc overexpression can down-regulate ATM expression via a human microRNA, miR-421, in MYCN-amplified neuroblastoma cells." (PMID 30657058, 2019). "Regulatory elements controlling ASCL1 expression are bound by LMO1, MYCN and the transcription factors GATA3, HAND2, PHOX2B, TBX2 and ISL1—all members of the adrenergic (ADRN) neuroblastoma core regulatory circuitry (CRC)." (PMID 31819055, 2019). "In contrast to the situation with MYCN amplification, ALK is the first kinase identified as a driver in neuroblastoma with real potential as a tractable therapeutic target, due to the number of inhibitors already available." (PMID 35582571, 2019). "Hence, persistent MycN expression during the maturation stages of sympathoadrenal precursors could result in blockage of apoptotic signaling and sustained proliferation eventually resulting in neuroblastoma development." (PMID 30760980, 2019). "Taken together, our study shows that ASCL1 is an integral member of the neuroblastoma CRC, essential for the formation of the feed-forward autoregulatory loop that drives the oncogenic transformation in concert with MYCN." (PMID 31819055, 2019). "We further reanalysed RNA-sequencing data from a series of neuroblastomas cohort and draw the same conclusion that ELOVL2 expression was significantly correlated with MYCN status." (PMID 31856871, 2019). "The fatty acid profile of MYCN-depleted neuroblastoma cells identified docosahexaenoic acid (DHA), an omega-3 polyunsaturated fatty acid with anti-tumor activity, significantly increased after MYCN depletion." (PMID 31856871, 2019). "Clinically, prognostic factors of neuroblastoma include factors such as age of diagnose, International Neuroblastoma Staging System (INSS) stage, MYCN status, and tumor histology." (PMID 31338261, 2019). "Our aim was to evaluate to what extent several of these well-established driver genes (MYCN, ALK) and neuroblastoma identity genes (PHOX2B) impact lincRNA expression." (PMID 30952905, 2019). "In conclusion, MYCN recruits the PRC1 complex, co-occupies the ELOVL2 promoter, mediates H2AK119ub and suppresses its transcription in neuroblastoma cells." (PMID 31856871, 2019).
neuroblastoma (continued). "Given that our results indicated that their expression is necessary for neuroblastoma cell invasion and that PTHLH knockdown reduces MYCN expression, we sought to identify the mechanism responsible for PTHLH production in neuroblastoma." (PMID 31293052, 2019). "Several genetic factors predictive of outcome in neuroblastoma have been identified, beginning in the 1980s with MYCN (or N-myc) status and DNA index, or tumor cell ploidy." (PMID 30754710, 2019). "We describe a mechanistic interaction in which ALK upregulates MYCN transcription, and discuss clinical trials emerging to develop transcriptional inhibitors of MYCN, and to identify effective inhibitors of ALK in neuroblastoma patients." (PMID 35582571, 2019). "As a key oncogene driver in neuroblastoma, MYCN (N-Myc) is also a critical regulator of NEPC and SCLC (small cell lung cancer, a poorly differentiated neuroendocrine lung cancer)." (PMID 32039001, 2019). "More recent, a refined genetically engineered mouse model with Cre-conditional induction of MYCN in dopamine β-hydroxylase-expressing cells termed LSL-MYCN;Dbh-iCre was shown to give rise to clinically relevant neuroblastomas in 75% of the mice." (PMID 30760980, 2019). "A panel of neuroblastoma cell lines, including CLB-BAR (amplified MYCN/ALK, ALKΔexon4-11), CLB-GE (amplified MYCN/ALK, ALK-F1174V), CLB-PE (amplified MYCN), and IMR-32 (amplified MYCN) was used to test alectinib." (PMID 31334113, 2019). "However, the function of MYCN in neuroblastoma fatty acid metabolism reprogramming remains unknown." (PMID 31856871, 2019). "Similar results were also observed in human neuroblastoma, where JQ1 targets BRD4 to regulate MYCN expression and induce cell death." (PMID 30906568, 2019). "Consistently, our results showed that MYCN knockdown down-regulated expression of the two subunits of FACT and resulted in marked increase in DNA damage in neuroblastoma cells." (PMID 31396265, 2019). "We have studied the efficacy of reversible and specific LSD1 inhibition with HCI-2509 in neuroblastoma cell lines and particularly the effect of HCI-2509 on the transcriptomic profile in MYCN amplified NGP cells." (PMID 29515779, 2018). "Whole chromosome 3 gains are a remarkably frequent recurring event in MYCN (46% of cases in our series, up to 40% of published cases), ALK (80% of cases) and Lin28b (100% of cases) driven murine neuroblastoma tumors." (PMID 29492199, 2018). "Neuroblastoma (NBL), a devastating pediatric cancer, is featured by frequent genomic amplification of MYCN, a member of the Myc oncogene family that is primarily expressed in the early stage of embryonic development and required for neural crest development." (PMID 29445162, 2018). "Moreover quantitative genomic alterations can be characteristic of certain cancers like the amplification of the super-enhancer MYCN (myelocytomatosis oncogene of neuroblastoma), a member of the MYC superfamily and of the 450 Ma old MYC interactom, driving most notably high risk neuroblastomas." (PMID 30171420, 2018). "Here, the authors investigate the epigenomics and transcriptomics of neuroblastoma, identifying TBX2 as a core regulatory circuitry component enhancing the reactivation of DREAM targets by MYCN/FOXM1." (PMID 30451831, 2018). "TERT mRNA expression in neuroblastoma cases was first detected in 2004; in that cohort, all cases with TERT expression had poor prognosis and were correlated with MYCN expression." (PMID 30326621, 2018). "In neuroblastoma, the polyamine regulating ODC1 was found co-upregulated with MYCN and correlates with poor outcome in neuroblastoma, suggesting a detrimental role in neuroblastoma biology." (PMID 29947893, 2018). "In our analysis, we confirm this high frequency in MYCN (7/15 cases), ALK (4/5 of cases) and Lin28b (6/6 of cases) driven neuroblastoma models." (PMID 29492199, 2018).
neuroblastoma (continued). "N-Myc (MYCN) belongs to the MYC family and was originally identified as being amplified in 20–30% of neuroblastoma tumours, but it is now well established that dysregulation of this transcription factor is common in many non-neuronal tumours." (PMID 29701689, 2018). "One study reported that increased c-MYC and/or MYCN expression defines highly aggressive, MYC- driven neuroblastoma." (PMID 30237861, 2018). "Here, we report on the further genomic characterization through exome sequencing and DNA copy number analysis of four of the currently available murine neuroblastoma model systems (ALK, Th-MYCN, Dbh-MYCN and Lin28b)." (PMID 29492199, 2018). "In vitro analysis demonstrated that the AURKA is required for the growth of MYCN-amplified neuroblastoma cell lines and the AURKA inhibitor alisertib (MLN8237) was able to inhibit the growth of neuroblastoma xenografts." (PMID 30200332, 2018). "Further studies have identified critical roles for chromatin structure and super-enhancers in neuroblastoma, and BET inhibitors have been shown to be effective against neuroblastoma via targeting of MYCN gene expression." (PMID 30384486, 2018). "To evaluate the effect of HCI-2509 on various poorly differentiated neuroblastoma cell lines, we studied cell lines that are MYCN amplified (LAN5 and NGP) and non-MYCN-amplified (SH-SY5Y and SK-N-SH)." (PMID 29515779, 2018). "Epigenetic targeting of MYCN expression with BET bromodomain inhibitors and histone deacetylase inhibitors is effective in reducing MYCN levels in neuroblastoma." (PMID 29515779, 2018). "In a zebrafish model of neuroblastoma, increased LMO1 synergizes with MYCN to promote tumorigenesis of aggressive phenotype neuroblastoma." (PMID 30200332, 2018). "In neuroblastoma, ALK activity has been shown to promote transcription of MYCN through phosphorylation of ERK5, a member of the MAPK family, in a PI3K-dependant manner thus integrating ALK effector signaling and MYC regulation." (PMID 29507657, 2018). "The authors revealed correlation between SNHG1 regulation and MYCN amplification and suggested SNHG1 as another indicator of neuroblastoma patient’s outcome and/or as an option for therapeutic targeting." (PMID 28178969, 2017). "MYCN and ALK copy numbers of subcutaneous neuroblastoma xenograft tumors were accurately determined from cell-free DNA in the mouse blood plasma." (PMID 29156716, 2017). "Another BET inhibitor, I-BET726, was shown to suppress MYCN as well as BCL-2 expression and accelerate apoptosis in neuroblastoma cell lines independently of MYCN copy number or expression level, and led to reduced tumor growth in vivo." (PMID 28358317, 2017). "We next evaluated ddPCR-based MYCN and ALK copy number assessment in blood plasma samples retrospectively collected at diagnosis from 10 neuroblastoma patients with known MYCN status." (PMID 29156716, 2017). "Interestingly, high levels of LSD1 and NDRG1 expression are mutually exclusive in neuroblastoma tumors and NDRG1 expression levels are significantly lower in MYCN-amplified NB samples." (PMID 27894074, 2017). "MYCN-amplification is present in ∼30% of all neuroblastomas and overexpression of N-MYC is sufficient to drive neuroblastoma-like tumors in animal models, highlighting the critical role of this oncogene in neuroblastoma development and progression." (PMID 29207623, 2017). "In a final validation step, we accurately distinguished MYCN and ALK copy numbers of the corresponding primary tumors using retrospectively collected blood plasma samples from 10 neuroblastoma patients." (PMID 29156716, 2017). "We established droplet digital PCR (ddPCR) protocols for MYCN and ALK copy number status in plasma from neuroblastoma patients." (PMID 29156716, 2017). "IMR32 cells are therefore MYCN amplified, and to assess the effects of CDDO on IMR32 cell differentiation pertaining to certain key genes regulated in neuroblastoma, RT-qPCR and western blotting was performed." (PMID 29018329, 2017).
neuroblastoma (continued). "Collectively, these findings demonstrated that high levels of LSD1 and NDRG1 expression are mutually exclusive in neuroblastoma, and the expression levels of NDRG1 are significantly lower in MYCN-amplified tumors." (PMID 27894074, 2017). "To further functionally confirm that TGFB1 is involved in directing neuroblastoma cell fate in a MYCN-dependant manner, we mined an RNAi knockdown screen targeting the druggable genome in SY5Y-MYCN cells." (PMID 28187790, 2017). "We assessed or re-assessed MYCN and ALK copy numbers in gDNA from a panel of 15 cell lines commonly used in neuroblastoma research during the development and validation of our ddPCR protocol." (PMID 29156716, 2017). "All of these variants are localized in the interacting domains that signal to MYCN, RAS, and RAC, pathways that are fundamental for the oncogenic potential of neuroblastoma cells." (PMID 28423360, 2017). "The neuroblastoma cell line WAC-2, a SH-EP subclone stably transfected with the MYCN gene, was used as a positive control." (PMID 29039746, 2017). "We recently demonstrated that targeting each of these pathways altered MYCN-amplified neuroblastoma viability and differentiation and that co-treatment with RA had additive or synergistic effects, suggesting that such combination therapies could be useful to treat MYCN-amplified neuroblastoma." (PMID 28187790, 2017). "The further examination in a large population requires to validate the role of ARID1B mutation on prognosis and possible mutual exclusivity between MYCN and ARID1 in neuroblastoma patients." (PMID 28521285, 2017). "The UCNR method is successfully applied on a large scale neuroblastoma study to detect up and down regulated microRNAs between MYCN amplified (MNA) and MYCN single copy (MNSC) tumor samples." (PMID 28817597, 2017). "While TGF-β can promote tumour progression in a number of adult cancers, we show that in neuroblastoma TGF-β is inhibited by MYCN overexpression and MYCN amplification." (PMID 28187790, 2017). "Here, we present ddPCR as an accurate method to assess MYCN and ALK copy numbers in tumor-derived cfDNA from blood plasma from neuroblastoma patients." (PMID 29156716, 2017). "As an initial step towards copy number detection in acelluar biosamples such as blood plasma, we analyzed MYCN and ALK amplification status from cfDNA in medium conditioned by neuroblastoma, medulloblastoma and colon adenocarcinoma cell lines." (PMID 29156716, 2017). "MYCN is a known transcriptional activator of TERT, yet MYCN amplifications were mutually exclusive with TERT rearrangements, as well as ATRX alterations, a gene associated with alternate lengthening of telomeres, suggesting that these alterations may share a similar role in neuroblastoma." (PMID 28587062, 2017). "An additional BET inhibitor, OTX015, has also been shown to reduce neuroblastoma growth in vitro and in vivo through the inhibition of BRD4, which occupies not only MYCN promoter, but also enhancers of MYCN target genes." (PMID 28358317, 2017). "The MYCN normal diploid status detected using gDNA was confirmed using cfDNA for the neuroblastoma cell lines, CLB-GA and SK-N-AS, as well as the MYC-amplified medulloblastoma and colon adenocarcinoma cell lines used as controls for MYCN assay specificity." (PMID 29156716, 2017). "To examine a possible role for PTEN in neuroblastoma growth we mated MYCN transgenic mice, which spontaneously develop neuroblastoma tumors, with PTEN+/− mice, to achieve MYCN PTEN+/− vs. MYCN PTEN+/+ mice." (PMID 28881723, 2017). "We specifically studied MYCN, MYBL2, BIRC5, BARD1 and AURKA, poor prognosis markers of neuroblastoma, and CCNA2 and CCNE1 genes, involved in general carcinogenesis." (PMID 28467792, 2017).